GSDMD (gasdermin D)
Diseases named in the same sentence as GSDMD in open-access papers (continued):
Sharing a sentence is not in itself a finding about the gene and the disease.
infection (continued). "Consistent with a temporally early role of caspase-4 in EPEC-induced pyroptosis, immunoblots showed caspase-4 activation in cell lysates within 1 h of infection, whereas cleaved caspase-1 and GSDMD proteins were detected at 3 and 5 h post-infection." (PMID 31018119, 2019). "Taken together, these data suggest that caspase-11/GSDMD-dependent pyroptosis triggered by B. abortus is important to infection restriction in vivo and contributes to immune cell recruitment and activation." (PMID 30589883, 2018). "GSDMD is expressed in a variety of cells, including gastrointestinal epithelium, immune cells (especially macrophages and dendritic cells), and plays an important role in the host defense against pathogen infection and inflammatory responses." (PMID 40704967, 2025). "Importantly, analysis of IAV responses at 24 h revealed that knockdown of GSDMD expression was sufficient to limit IL-1β secretion following HKx31 infection." (PMID 40481027, 2025). "However, the induction of effector molecules involved in inflammasome activation, including CASP1 and GSDMD, occurs later in the infection, coinciding with high levels of DENV-2 replication." (PMID 40934228, 2025). "Tnfr1 deficiency and TrifLps2 mutation protected macrophages from cell lysis at 3 h (Fig. EV1C) and 5 h post-infection and these cells displayed reduced cleavage of caspase-8, caspase-3, GSDMD as well as the fluorogenic caspase-3/7 substrate (Fig. EV1D) compared to WT macrophages." (PMID 40128366, 2025). "Interestingly, we have previously reported that IAV infection of human bronchial epithelial cells also results in cleavage of GSDMD, as well as the effector caspase-1 at 24 h post-infection." (PMID 40481027, 2025). "Similarly, LDH release was only significantly compromised following HKx31 infection when both GSDMD and GSDME were suppressed." (PMID 40481027, 2025). "Although it is important to note that GSDMD silencing also limited IL-1β release in response to HKx31 infection in a separable manner, suggesting that other lytic and non-lytic secretion mechanisms are in play in lung epithelial cells to promote damaging inflammation." (PMID 40481027, 2025). "Additionally, the cleaved, pore-forming form of GSDMD (GSDMD-CL) was detected 24 h after infection with Pg." (PMID 41221328, 2025). "However, ΔeseB-D, ΔeseB, ΔeseC, and ΔeseD were unable to induce host cell death, IL-1β release, Casp1 activation, or GSDMD cleavage following infection." (PMID 39951384, 2025). "The roles of GSDMD in inflammation and immune responses to infection are well documented." (PMID 38898209, 2024). "Infection with L. mexicana induced GSDMD cleavage, contrary to the other New World spp." (PMID 39250503, 2024). "The underlying mechanism may involve inflammasome activation, and triggers immune cell pyroptosis defense against pathogen infection via caspase-1/GSDMD pathway." (PMID 39011036, 2024). "These cytokines are known to play a crucial role in the host defense against infection and may be released through pores formed by the N-terminal oligomerization of GSDMD." (PMID 38807373, 2024). "Following adoptive transfer at the time of infection, a higher frequency of Gsdmd-/- compared to C57BL/6 neutrophils was observed 24h later in the infected ear, indicating prolonged survival of GSDMD-deficient neutrophils." (PMID 39250503, 2024). "Similarly, the caspase inhibitor Z-VAD-FMK inhibited the cleavage of GSDMD and IL-1β production during P1/7 infection." (PMID 39334337, 2024). "To test whether M84 can reduce pyroptosis, we analyzed the level of the N-terminal fragment of cleaved GSDMD in J774A.1 macrophages at 10 and 24 h post infection." (PMID 38278864, 2024). "Caspase-1, caspase-4, and caspase-11 cleave the GSDMD in response to infection." (PMID 38429762, 2024).
infection (continued). "In a study carried out with L. amazonensis in murine macrophages, it was demonstrated that Gasdermin D is activated in the initial stages of infection (2 h), which leads to transient cell permeabilization and potassium efflux, promoting the activation of the NLRP3 inflammasome." (PMID 38743668, 2024). "Indeed, directly infected neutrophils are observed in vivo and infection of neutrophils in vitro induces release of DNA and tissue-damaging enzymes that is largely dependent on GSDMD." (PMID 38553499, 2024). "Therefore, GSDMD has a complex regulatory role in maintaining the intestinal mucosal immune barrier against pathogen infection and preserving homeostasis." (PMID 38807373, 2024). "If enough GSDMD pores form, the cell undergoes pyroptosis, a lytic, inflammatory form of cell death that releases danger signals, alerting the environment during an ongoing infection." (PMID 39250503, 2024). "Among these, GSDMD is well known for its role in antibacterial infection." (PMID 39219679, 2024). "Moreover, IECs and lamina propria cells both employ GSDMD to restrict S.Tm tissue infection and to switch the gut mucosa as a whole toward an anti-S.Tm state." (PMID 37988464, 2023). "Lastly, we also observed cleavage of GSDMD downstream of inflammasome activation by MVA infection." (PMID 38065956, 2023). "To test whether GSDMD is required for cell death and inflammasome-dependent cytokine release during Δ6 Yptb infection, we pretreated Caco-2 cells with disulfiram, a chemical inhibitor of GSDMD pore formation." (PMID 37615436, 2023). "GSDMD-mediated infection clearance was demonstrated in several intracellular bacteria." (PMID 37009510, 2023). "We detected gasdermin D cleavage from FliCON infection in as little as 1–2 hpi." (PMID 38055781, 2023). "Moreover, NETs were shown to release S100A8/A9 to further induce GSDMD-dependent platelet pyroptosis, forming a deleterious positive feedback loop that exacerbates the inflammatory response after infection." (PMID 37275856, 2023). "Both GSDMD and NAIP/NLRC4 limit S.Tm loads in the deeper gut mucosal tissue, as well as in systemic organs, and prevent the loss of epithelial barrier integrity by 48 to 72 h of infection." (PMID 37988464, 2023). "Compared with macrophages, there are relatively few studies examining the role of GSDMD or other Gasdermin family members in neutrophils, even though neutrophils vastly outnumber other cells recruited to sites of inflammation and infection, especially at early time points." (PMID 37730693, 2023). "Therefore, as Gsdmd–/– mice displayed transiently enhanced susceptibility to C. rodentium around 14 dpi, we evaluated the effect of GSDMD on colon inflammation at this stage of infection." (PMID 37080966, 2023). "Furthermore, Shigella IpaH7.8, a bacterial ubiquitin ligase, was identified as an inhibitor of GSDMD-dependent pyroptosis and sustains pathogen infections by targeting human GSDMD-NT domain and ubiquitinating GSDMD for proteasomal degradation." (PMID 37275856, 2023). "To investigate whether one or several Gasdermins mediate this protection, we performed littermate-controlled infections with mice deficient in individual Gasdermins (GSDMA1-3-, GSDMC1-4-, GSDMD-, or GSDME-deficient mice)." (PMID 37988464, 2023). "Moreover, whole colon lysates from C. rodentium-infected mice at 7 days post-infection (dpi) displayed GSDMD cleavage." (PMID 37080966, 2023). "Interestingly, only infected cells were PI+ after 2 h infection, suggesting that Leishmania internalization in macrophages is required for inflammasome activation and the transient GSDMD-mediated pore formation." (PMID 36828815, 2023). "Additionally, mRNA levels of pyroptosis-related genes (NLRP3, ASC, caspase-1, GSDMD, IL-18, and IL-1β) in the kidneys with W24Δhcp1 infection are considerably lower than in those with WT W24 infection." (PMID 36977062, 2023).
infection (continued). "Besides, monocytes infection activates AIM2 inflammasome, caspase-1 and GSDMD cleavage, and the expression level of GSDMD on the cell membrane and cytoplasm of monocytes is linked with the severity of infection." (PMID 37063905, 2023). "In other work, neutrophils infected with a mutant strain of Shigella flexneri lacking a key type 3 secretion system (T3SS) virulence factor (ΔOspC3 mutant) also activated caspase-11 and GSDMD to induce pyroptosis, which again proved important in limiting infection." (PMID 37939552, 2023). "While GSDMA, C, and E appear dispensable, we show that GSDMD i) restricts S.Tm loads in the gut tissue and systemic organs, ii) controls gut inflammation kinetics, and iii) prevents epithelium disruption by 72 h of the infection." (PMID 37988464, 2023). "However, canonical pyroptosis due to the cleavage of GSDMD usually occurs in macrophages upon infection of exogenous pathogens, which is essential for pathogen clearance." (PMID 37528490, 2023). "In recent study, we showed that caspase-11/GSDMD-dependent pyroptosis process triggered by B. abortus contributed to the restriction of infection in vivo by assisting in the recruitment and activation of immune cells such as neutrophils, macrophages, and dendritic cells." (PMID 36532444, 2022). "Furthermore, the spleen of GSDMD-/- mice suffered greater damage than GSDMD+/+ mice after SEZ infection." (PMID 36311722, 2022). "infection triggered neutrophil and macrophage pyroptosis via a GSDMD/E-mediated pathway." (PMID 35844522, 2022). "We hypothesized that macrophages were induced to undergo GSDMD-mediated pyroptosis after SEZ infection." (PMID 36311722, 2022). "Moreover, all GSDMD-/- mice had succumbed before the sixth day after infection, while 40% of GSDMD+/+ mice still survived at the end of the 10 days post-infection." (PMID 36311722, 2022). "Infection of WT and GsdmD-/- neutrophils with PP34ExoUS142A showed that Glycine did not modify neutrophil histone citrullination and DNA decondensation upon PP34ExoUS142A infection, although it efficiently protected cells from LDH release without affecting IL-1β release." (PMID 35849616, 2022). "Additional hallmark pyroptotic processes, such as the cleavage and release of Caspase-1 and GSDMD, were apparent upon infection of BMDMs with the Δvprh/Δhns1 strain; however, they were undetected upon inactivation of T6SS3 or upon the addition of inflammasome inhibitors." (PMID 36155655, 2022). "The active end of caspase-1 and gasdermin D (GSDMD) were highly expressed even after infection." (PMID 35761358, 2022). "Several studies revealed the role of GSDMD in host defense against infections." (PMID 35844522, 2022). "At 6 and 12 h post-infection, the mRNA expression levels of caspase-3, caspase-1, GSDMD, RIPK3, MLKL, NLRP3, IL-1β, and IL-18 were upregulated in RAW264.7 macrophages infected with either E. faecalis CA1, CA2, or OG1RF strains compared to the levels in the control group." (PMID 34513732, 2021). "To determine whether pyroptosis occurs in TGEV infection, we initially monitored the mRNA expression of GSDMD after TGEV infection at different multiplicities of infection (MOIs) in swine testis (ST) cells." (PMID 35100869, 2021). "Interestingly, although Gasdermin D levels decreased at day 4 post infection in the lungs, its expression kept increasing in the brainstem, possibly due to a difference in infection kinetics between the tissues." (PMID 34608167, 2021). "Additionally, we found that GSDMD in PE was secreted by NCs, manifested by the correlation analysis and cell infection results." (PMID 34163438, 2021). "Moreover, GSDMD pores mediate the extracellular release of danger signals and proinflammatory cytokines that recruit immune cells to the site of infection, leading to the elimination of pathogens." (PMID 33634141, 2021). "In addition, the level of GSDMD is also increased in amniotic fluid from women with intra‐amniotic inflammation/infection." (PMID 34590363, 2021).
infection (continued). "The interplay between mROS, GSDMD and autophagy during different infections may differ which licenses more investigation." (PMID 33441602, 2021). "Thus, significant amounts of IL-1β can still be released in Gsdmd-/- mice via GSDMD-independent macrophage lytic death to maintain host responses to C. albicans, thereby alleviating infection in these mice." (PMID 34795266, 2021). "GSDMD cleavage occurred as early as 4 h after the infection and continued to increase thereafter." (PMID 34795266, 2021). "We speculate that upon infection of hMDM with T3SS/flagellin-deficient S. Typhimurium, IL-1β and IL-18 are processed in a caspase-8–dependent manner and released in a GSDMD-independent way." (PMID 33380493, 2021). "Therefore, there is increasing interest in pursuing GSDMD as a new therapeutic target for anti-infection treatment." (PMID 34899666, 2021). "Interestingly, T. gondii tachyzoites induced increased expression of processed N-terminal GSDMD (GSDMD-NT), indicating that GSDMD is cleaved during infection." (PMID 34607465, 2021). "Thus, TLR2 activation by RSV and ROS generation during infection will promote formation of ASC-NLRP3 inflammasome complex that activates caspase-1 for Gasdermin-D mediated pyroptosis." (PMID 32854254, 2020). "Overall, our results converge to a novel pathway, which relies on influx of Ca2+ through the plasma membrane during infection with an extracellular pathogen, in a Tir-dependent manner, leading to LPS internalisation followed by caspase-4-mediated GSDMD cleavage." (PMID 33378358, 2020). "Therefore, GSDMD and multiple caspases (CASP1, CASP7 and CASP8) operate downstream of the NAIP5/NLRC4 inflammasome for restriction of infection by pathogenic bacteria." (PMID 31251782, 2019). "Moreover, these analyses revealed that MLN from MNV-infected Stat1-/-Nlrp3+/- mice also displayed Nlrp3-dependent GSDMD cleavage after MNV infection, indicative of pyroptosis." (PMID 31017981, 2019). "Mice lacking either caspase-11 or GSDMD were significantly more susceptible to infection with B. abortus than caspase-1 knockout or wild-type animals." (PMID 30589883, 2018). "To determine whether CSFV infection had an effect on pyroptosis of PBMCs, we infected the PBMCs of pigs with different doses of CSFV (MOIs of 0.1, 1, and 10) and detected the expression of GSDMD and its cleavage after infection." (PMID 30013955, 2018). "Also, the expression level of GSDMD positively correlated with the infection level by CSFV, which indicated that CSFV infection induced pyroptosis in PBMCs." (PMID 30013955, 2018). "Additionally, increased expression of inflammasome-related markers like Absent In Melanoma 2 (AIM2), NLR Family Pyrin Domain Containing 3 (NLRP3), and GSDMD in monocyte-macrophages suggested a higher incidence of pyroptosis during severe SARS-CoV-2 compared to moderate infection." (PMID 39928675, 2025). "Additionally, we observed that ΔnleB/espL triggered enhanced macrophage cytotoxicity, caspase-8 and caspase-1 processing, GSDMD cleavage and IL-1β maturation compared to ΔnleB infection in LPS-primed macrophages, while ΔnleB/espL complemented with nleB or espL caused less cell lysis (Fig. EV5A)." (PMID 40128366, 2025). "Modifications of virulence factors may also occur during extended in vitro culture time, and we excluded this for L. mexicana, as vector competent parasites of the same strain, that successfully developed a mature infection in sand flies, induced similar neutrophil GSDMD cleavage." (PMID 39250503, 2024). "We then asked whether virus-expressed Mpro is able to cleave GSDMD in the context of infection." (PMID 38932190, 2024). "Interestingly, we could not detect Mpro cleaved fragments of endogenous GSDMD in virus infected cells, although we did observe a decrease in full length GSDMD during HCoV-229E infection." (PMID 38932190, 2024). "Thus, GSDMD cleavage in neutrophils differs following infection with distinct Leishmania spp." (PMID 39250503, 2024).
infection (continued). "Thus, we examined whether GSDMD was involved in neutrophil recruitment to the lungs during infection using flow cytometry." (PMID 38553499, 2024). "To directly address whether this epithelial GSDMD phenotype at 18 h p.i. contributes to elevated S.Tm loads in cecum tissue, and at systemic sites later during infection, we again generated BM chimeras in which we replaced the BM of GsdmD+/− and GsdmD−/− littermates with WT (CD 45.1+) BM." (PMID 37988464, 2023). "It is likely that GSDMD in macrophages and neutrophils i) promotes cell death, ii) accelerates mucosal inflammation, and iii) traps S.Tm in pore-induced intracellular traps (PITs) and NETs, respectively, thereby preventing subsequent re-infections into adjacent host cells." (PMID 37988464, 2023). "In addition to its other functions, GSDMD has a pleiotropic role in infection models." (PMID 37664463, 2023). "The internalization of the parasites after 2 h of infection was not affected by the deficiency of GSDMD, NLRP3, or Caspase-1/11, but macrophages lacking any of these genes were more susceptible to intracellular replication of the parasite as observed after 48 h and 72 h of infection." (PMID 36828815, 2023). "Moreover, in contrast to our observations in uninfected mice, whole colon lysates of C. rodentium-infected mice showed the presence of mature IL-18 as well as cleaved caspase-1 and GSDMD, indicating that this infection induced inflammasome activation in the colon." (PMID 38090573, 2023). "Similarly, hepatitis C virus (HCV) caused hepatocyte pyroptosis soon after infection, but in the absence of GSDMD, HCV activated a caspase-3-mediated apoptotic program." (PMID 35844522, 2022). "Active inflammasomes also regulate gasdermin D activation resulting in pore formation and IL-1β release in the context of pyroptosis, which might account for the membrane damage we observed in monocytes after 2 h infection." (PMID 35509315, 2022). "Recent reports indicate that bacterial effectors or viral proteases can also target GSDMD for ubiquitination and degradation, or inactivating proteolysis, respectively, to block host cell death and enable efficient infection, while other viral proteases may activate GSDMD killing activity." (PMID 35608339, 2022). "Thus, it is reasonable to hypothesize that polyubiquitination of the common component of GSDMD effectively regulates pyroptosis in response to infection and danger signals." (PMID 35115505, 2022). "Thus, it has been recently described that GSDME, a protein related with pyroptosis and IL-1β release, is activated in neutrophils in a RIPK1-dependent manner and that the FADD-RIPK1-caspase 8 complex is recruited after infection to cleavage GSDMD and initiates the inflammatory cell death." (PMID 35716229, 2022). "Additionally, the S. Typhi ΔtviA and tviA-REP mutant strains induced higher levels of caspase-1, IL-1β, and gasdermin D cleavage as assessed by Western blot compared to the WT S. Typhi strain, indicating greater inflammasome activation upon infection with these mutants." (PMID 33651854, 2021). "However, consistent with our previous result, we observed significantly higher levels of activated gasdermin D in R. africae-infected THP-1 macrophages than in the other infection conditions at 12 and 24 hpi, suggesting that pyroptotic events are triggered earlier by R. africae." (PMID 34935429, 2021). "Therefore, we speculate that caspase-11/GSDMD-dependent pyroptosis contributes to immune cell recruitment and activation in response to B. abortus and this process may promote infection control in mice, although formal validation is still required." (PMID 30589883, 2018). "We found that RSV-induced plasma membrane rupture and IL-1β release were unaffected by GSDMD knockout, but abolished upon GSDME deletion, indicating that RSV promotes GSDME-dependent pyroptosis for IL-1β secretion in late infection." (PMID 41576161, 2026).